ACE (angiotensin I converting enzyme)
Diseases named in the same sentence as ACE in open-access papers (continued):
Sharing a sentence is not in itself a finding about the gene and the disease.
Hypertension (continued). "Blocking angiotensin II synthesis using ACE inhibitors is considered as the main pharmacological intervention in the management of hypertension and related pathologies." (PMID 39057713, 2024). "The third most significant risk factor for serious health issues, including early mortality, globally is hypertension, or high blood pressure, which is a result of the angiotensin-converting enzyme (ACE), a crucial component in blood pressure management." (PMID 39421675, 2024). "Pharmacological treatments for hypertension include antihypertensive medications, such as angiotensin-converting enzyme (ACE) inhibitors, angiotensin II (AngII) receptor blockers (ARBs), calcium channel blockers (CCBs), and diuretics." (PMID 39767646, 2024). "Antenatal glucocorticoid exposure causes offspring hypertension, coinciding with the upregulation of renin, PRR, ACE, and AT1R expression." (PMID 38542273, 2024). "Some of the patients were under home medical therapy due to their comorbidities (e.g., ACE inhibitors for hypertension treatment)." (PMID 39329758, 2024). "Food-derived angiotensin-converting enzyme (ACE)-inhibitory peptides have the potential to both prevent and treat hypertension." (PMID 39517176, 2024). "Angiotensin-converting enzyme (ACE) inhibitors or angiotensin receptor blockers (ARBs) should be taken into consideration to treat new-onset hypertension in patients with renal infarction." (PMID 39011195, 2024). "In this cohort, the median CCI was 1.5, with most patients having hypertension and hyperlipidemia and taking statins or ACE inhibitors during baseline." (PMID 39671357, 2024). "As mentioned, lentil proteins and their hydrolysates exhibit ACE-inhibitory activity, which is important for hypertension control." (PMID 38501131, 2024). "The mean duration of hypertension was 7.92 ± 4.06 years, and the most commonly used medication among participants (27.8%) was ACE Inhibitors." (PMID 39619176, 2024). "Enalapril is an angiotensin-converting enzyme (ACE) inhibitor and is widely used in therapeutic interventions for hypertension." (PMID 38887391, 2024). "Among the most common treatments are drug therapies for hypertension, such as angiotensin-converting enzyme (ACE) inhibitors, angiotensin II receptor blockers, calcium channel blockers, and diuretics." (PMID 39728459, 2024). "In the treatment of hypertension, ACE inhibition is a crucial therapeutic approach, because ACE facilitates the formation of angiotensin II, a potent vasoconstrictor." (PMID 39683849, 2024). "Antihypertensive medications, including angiotensin-converting-enzyme (ACE) inhibitors, angiotensin receptor blockers (ARBs), and calcium channel blockers, effectively manage hypertension and offer additional benefits for metabolic health." (PMID 39310549, 2024). "The aim of this study is to evaluate the antihypertensive potential of HS extract through the in vitro inhibition assay of angiotensin-converting enzyme (ACE) and hypertension precursor enzymes, as well as to assess its in vivo diuretic activity." (PMID 38397511, 2024). "Overall, these findings suggest that LLY possesses potent ACE-inhibiting activity and holds potential for application in hypertension treatment." (PMID 39684732, 2024). "While thiazide diuretics are a standard first-line option for managing hypertension, other first-line, efficacious classes of medications exist, including CCBs, ACE inhibitors, ARBs, and beta-blockers." (PMID 39100000, 2024). "Its effectiveness and wide recognition in ACE inhibition studies highlight its therapeutic potential in managing hypertension." (PMID 39452857, 2024). "Two active peptides (FRVW and LPYY) found in the meat of P. fucata can effectively inhibit ACE and have potential value as a treatment for hypertension." (PMID 39195461, 2024).
Hypertension (continued). "The angiotensin-I converting enzyme (ACE) plays a pivotal role in hypertension, and while ACE inhibitors are conventional in hypertension management, synthetic medications often carry undesirable side effects." (PMID 38540933, 2024). "Two genes were associated with the development of hypertension in the Han Chinese population, namely, AGT (rs3789678) and ACE (rs4305) [83••]." (PMID 38411777, 2024). "Research indicates the potential of peptides derived from human milk as therapeutic agents against hypertension, due to their ACE-inhibitory activity and ability to permeate Caco-2 monolayer cells." (PMID 38731669, 2024). "Inhibiting the ACE can help manage hypertension, making it a target for many therapeutic interventions." (PMID 39272610, 2024). "In the context of modern medicine, ACE inhibitors have effectively managed ACE activity and treated hypertension." (PMID 38575133, 2024). "Inhibited ACE translates into less constricted muscular walls of small arteries, which in turn is conducive to relieving hypertension." (PMID 39125365, 2024). "One AZ patient with a history of dyslipidemia and hypertension, for which he was taking an ACE inhibitor, developed hypotension, tachycardia, diarrhea, and vomiting after sustaining a bite to the lower leg while walking his dog." (PMID 38047156, 2024). "Univariate regression analysis showed that hypertension (OR 15.2), diabetes (OR 7.05), and obesity (OR 4.14) are the most significant predictors of CXR infiltrate severity, together with ACE D/D polymorphism (OR 3.58) and PTX3 serum level (OR 1.26)." (PMID 39062191, 2024). "ACE inhibitors, such as captopril, enalapril, and perindopril, are routinely prescribed to treat hypertension." (PMID 38474055, 2024). "In the case of hypertension, flavonoid glycosides offer promising avenues for developing novel ACE inhibitors." (PMID 39771606, 2024). "Angiotensin-converting enzyme (ACE) inhibitors are used primarily in the treatment of hypertension, heart failure, and in the acute phase of myocardial infarction." (PMID 38543146, 2024). "The use of angiotensin-converting enzyme inhibitors (ACE inhibitors) represents a major step forward in the treatment of arterial hypertension." (PMID 38921258, 2024). "These ACEiPs can inhibit ACE in vitro and even exhibit similar or better blood-pressure-lowering effects than Captopril (an ACE inhibitor for the treatment of hypertension) in animal experiments." (PMID 39593966, 2024). "In the multivariate regression model, important predictors of death were hypertension and PTX3, while ACE I/I polymorphism reduced the probability of death." (PMID 39062191, 2024). "The early post-weaning administration of ACE inhibitors, such as captopril or perindopril, for a duration of 3 weeks has demonstrated efficacy in preventing the onset of hypertension in adult SHRs." (PMID 38542273, 2024). "Ramipril is an ACE inhibitor that is frequently prescribed for hypertension, as ACE produces angiotensin II, which, in turn, elevates blood pressure." (PMID 38275965, 2024). "Relevant inhibitors of this axis, such as ACE inhibitors captopril and enalapril, and Ang receptor blockers (ARBs) telmisartan, valsartan, and irbesartan, are commonly used as drugs to treat hypertension." (PMID 39247619, 2024). "Another example is the burpitides lyciumin A and lyciumin B, derived from Lycium chinense, which have been reported to inhibit angiotensin-converting enzyme (ACE) and renin, highlighting their potential for hypertension management." (PMID 39852121, 2024). "This suggests that AEPM holds significant potential as a natural ACE inhibitor for the prevention of hypertension." (PMID 39598284, 2024). "HS calyxes are, therefore, a good candidate for nutraceutical use, not only to cure but also to prevent hypertension by inhibiting blood pressure-regulating enzymes such as ACE." (PMID 38397511, 2024).
Hypertension (continued). "The presence of hypertension in this case highlights the importance of selecting antihypertensive medications carefully, as some such as ACE inhibitors or beta blockers, have been reported to potentially trigger conditions like PV." (PMID 39723273, 2024). "Because of their renal protective effects and positive prognostic effects in the elderly, angiotensin-converting enzyme (ACE) inhibitors are often administered as one of the first-line therapies to treat arterial hypertension." (PMID 38790943, 2024). "Hypertension (OR 6.91), PTX3 (OR 1.47), and ACE I/I polymorphism (OR 0.09) are significant predictors of poor outcomes." (PMID 39062191, 2024). "The therapeutic suppression of ACE has been an essential component in the management of hypertension and other cardiovascular disorders and conditions connected to it." (PMID 39452857, 2024). "Apart from limiting salt intake and following a balanced Mediterranean diet, hypertension can be treated with drugs, such as angiotensin-converting enzyme (ACE) inhibitors and angiotensin receptor blockers (ARBs)." (PMID 38337372, 2024). "In a promising 2007 study, preoperative treatment of hypertension with ACE inhibitors yielded a lower recurrence rate in patients with cSDH." (PMID 39200732, 2024). "All patients with hypertension were under therapy with at least one anti-hypertensive agent (predominantly with ACE inhibitors/ARBs: 65%; followed by diuretics: 36%; beta-blockers 29%; and 2% with MRAs)." (PMID 38528043, 2024). "ACE-2 is located in the vascular endothelium of the lungs and has the opposite functions to ACE, promoting vasodilation and decreasing hypertension, thus having a cardio-protective role." (PMID 38541641, 2024). "In the multivariate regression analysis, only hypertension, PTX3, and ACE D/D polymorphism remained important predictors of the severity of CXR infiltrates." (PMID 39062191, 2024). "We report the case of a 48-year-old Indian male with a history of well-controlled plaque psoriasis who experienced severe flare-ups after initiating ACE inhibitor therapy for hypertension." (PMID 39364528, 2024). "Captopril, an ACE inhibitor, reduces blood pressure and enhances glucose metabolism in the heart, providing cardioprotective benefits in hypertension." (PMID 39201496, 2024). "Most importantly, both SWs have ACE inhibitory activity, which is important to reduce hypertension and categorize SWs as a functional food." (PMID 39062831, 2024). "The ALLHAT trial compared four major types of medications calcium channel blocking drugs, ACE inhibitors, and diuretics such as thiazide and alpha-blockers are used to treat hypertension, in more than 42,000 participants with hypertension." (PMID 38716006, 2024). "ACE inhibitors, including captopril, lisinoporil, perindopril, and enalapril, are commonly prescribed for patients with hypertension." (PMID 39598284, 2024). "It is well established that ACE inhibitors, which are widely used to treat hypertension, congestive heart failure, and diabetic nephropathy, lead to a buildup of bradykinin." (PMID 38546304, 2024). "The purpose of this study was to optimize the protease treatment condition to produce PPH with high ACE- and renin-inhibitory activity for possible food therapy of hypertension." (PMID 39000571, 2024). "Activation of the classical renin–angiotensin system (RAS) pathway—specifically, the angiotensin-converting enzyme (ACE)-angiotensin II (Ang II)-angiotensin type 1 receptor (AT1R) axis—promotes the development of hypertension." (PMID 39339768, 2024). "Myocarditis associated with ICI use has been more commonly reported in patients with history of hypertension, tobacco use, and certain ubiquitous medication such as ACE inhibitors and statins." (PMID 39459012, 2024). "Further, a study involving elderly patients with arterial hypertension reported eight cases of severe drug-drug interactions between unspecified ACE inhibitors and allopurinol." (PMID 38333456, 2024).
Hypertension (continued). "Inhibition of ACE is a cornerstone in the management of hypertension, cardiovascular diseases, and renal disorders." (PMID 39046229, 2024). "Overexpression of the ACE gene resulted in exaggerated ACE biosynthesis, increased ACE activity, and hypertension development." (PMID 38474055, 2024). "While ACE inhibitors are effective for managing hypertension and heart failure, their potential to induce or worsen psoriasis should not be overlooked, particularly in patients with a known predisposition to the condition." (PMID 39364528, 2024). "ACE inhibitors are crucial components in the management of arterial hypertension and various cardiovascular conditions." (PMID 38543146, 2024). "That is why pharmacologically inhibiting the classic RAS pathway using ACE inhibitors and angiotensin II receptor blockers (ARBs) has been a well-established strategy to treat hypertension." (PMID 38397935, 2024). "PKC activation promotes ACE gene transcription and secretion in endothelial cells, playing a significant role in the development of hypertension." (PMID 39598284, 2024). "A European-based study revealed a directly proportional relationship between ACE (rs4305) and hypertension." (PMID 38411777, 2024). "For example, captopril, an angiotensin-converting enzyme (ACE) inhibitor derived from the venom of the Brazilian pit viper (Bothrops jararaca), is a widely used drug for treating hypertension and heart failure." (PMID 39591213, 2024). "ACE inhibitors, ARBs, β-blockers, calcium channel blockers, and antiarrhythmic agents manage hypertension, heart failure, and arrhythmias by improving blood flow and reducing cardiac workload." (PMID 39273041, 2024). "The involvement of the ACE2 receptor in the viral replication system also raises concerns about the use of ACE inhibitor drugs in the treatment of hypertension." (PMID 39200770, 2024). "His medical history included type I diabetes mellitus, poorly controlled with biphasic isophane insulin suspension, and essential hypertension treated with an angiotensin-converting enzyme (ACE) inhibitor." (PMID 39440165, 2024). "ACE inhibitors have been shown to effectively reduce high blood pressure and exert renal and cardioprotective effects." (PMID 39273366, 2024). "A standardized herbal medicinal product containing roselle has effectively reduced blood pressure, lowered triglycerides, and decreased mean serum renin and ACE activity in patients with grade 1 essential hypertension." (PMID 39273041, 2024). "For this reason, ACE inhibitors are a therapeutic target against high blood pressure that reduce the concentration of angiotensin II and thus lower blood pressure." (PMID 38337933, 2024). "In fact, ACE inhibitors, the drugs used for the treatment of hypertension and congestive heart failure, were developed from the venom of this species." (PMID 38790989, 2024). "Subsequently, synthetic ACE inhibitors such as captopril, enalapril, and lisinopril have been widely used to manage essential hypertension despite potential adverse effects such as hypotension, hyperkalemia, decreased renal function, and angioedema." (PMID 39595018, 2024). "BK is a substrate of ACE, an enzyme which has mostly been investigated with regard to hypertensive disorder, but which has also been of interest in the recent COVID-19 pandemic, because its counter-regulator ACE2 is the SARS-CoV-2 entrance port." (PMID 38790989, 2024). "It is well known that excess angiotensin-I-converting enzyme (ACE) leads to high blood pressure, and current ACE inhibitors such as captopril, benazepril, enalapril, quinapril and univasc, are widely used in clinical practice for treating hypertension." (PMID 38384691, 2024). "A variety of medications can be prescribed to manage high blood pressure, we created separate codelists for ACE inhibitors (n=2,289), angiotensin receptor blockers (n=3,731), calcium channel blockers (n=4,490) and thiazide-like diuretics (n=3,536)." (PMID 38626934, 2024).
Hypertension (continued). "Given their renoprotective effects, ACE inhibitors and ARBs are first-line options for patients with high blood pressure and chronic kidney disease or heart failure." (PMID 39100000, 2024). "Angiotensin-converting enzyme (ACE) is responsible for converting angiotensin I (AT1) to angiotensin II (AT2), which plays a role in hypertension and has been directly implicated in the pathogenesis of Alzheimer's disease." (PMID 37746412, 2023). "The first single-pill combination of a beta-blocker and ACE inhibitor became available in 2016 in the form of bisoprolol/perindopril (Cosyrel®) and is indicated in arterial hypertension, stable CAD, and/or heart failure." (PMID 34533690, 2023). "Guidelines for the management of hypertension in Japan include Ca channel blockers, ARBs, ACE inhibitors, and diuretics as first-line drugs for hypertension management." (PMID 38066634, 2023). "ramosissima, M. nodiflorum, M. crystallinum, and I. crithmoides showed ACE-inhibitory activity, an important target control for hypertension." (PMID 37371891, 2023). "According to statistical data, the use of ACE inhibitors (ACEis) or sartans is one of the most used therapeutic approaches for patients with hypertension." (PMID 37892676, 2023). "ACE inhibition is fundamental to blood pressure regulation; indeed, ACE is the target of the pharmacological treatment of hypertension and related cardiovascular diseases." (PMID 37508379, 2023). "This study provides valuable information on the potential of alpha-linolenic acid-rich flaxseed oil as an ACE regulator, suggesting possible benefits in hypertension management." (PMID 37964928, 2023). "We controlled for participants taking anti-hypertension-specific medications (namely, ACE Inhibitors, ARBs and Beta-Blockers) as they directly impact PWV and they were among the most commonly taken in our sample." (PMID 38162458, 2023). "This safety profile made ARBs more advantageous compared to ACE inhibitors in treating patients with hypertension." (PMID 37299008, 2023). "Currently, first-line pharmacological treatments for hypertension include monotherapy or combination therapy using ACE inhibitors and angiotensin AT1 receptor blockers (ARBs), thiazide diuretics, and long-acting dihydropyridine calcium channel blockers." (PMID 37404743, 2023). "In clinical practice, angiotensin receptor blockers (ARBs) and angiotensin-converting enzyme (ACE) inhibitors (ACEIs) are commonly applied in the treatment of hypertension and other cardiovascular diseases." (PMID 37291545, 2023). "Both upregulated gene expressions (e.g., NOS3) and downregulated gene expressions (e.g., ACE) are shown here for this hypertension example with nutrient and ranking information also provided." (PMID 37305078, 2023). "ACEIs are primarily used to treat hypertension and heart failure, preventing ACE-mediated conversion of angiotensin I to angiotensin II and the resulting increase in blood pressure." (PMID 36831338, 2023). "As an essential component of RAS, genetic variation in ACE genes plays a pivotal role in the formation of hypertension." (PMID 37091860, 2023). "Two herbal extracts, BM and DM, strongly inhibited ACE, the key enzyme contributing to hypertension." (PMID 38066118, 2023). "Current ESC/ESH guidelines for the management of newly diagnosed arterial hypertension, recommend dual drug therapy with either an ACE inhibitor or ARB, and a thiazide diuretic or CCB." (PMID 36817852, 2023). "In adults with PWS with albuminuria and hypertension, an ACE inhibitor or angiotensin-II receptor antagonist should be the first line of treatment due to their renoprotective effects." (PMID 37547314, 2023). "Lisinopril, an antihypertensive drug approved by US Food and Drug Administration for the management of hypertension, is an ACE inhibitor that prevents the conversion of AGE I to AGE II." (PMID 37553559, 2023).